NCKAP1L (NCK associated protein 1 like)
Description:
Essential hematopoietic-specific regulator of the actin cytoskeleton (Probable). Controls lymphocyte development, activation, proliferation and homeostasis, erythrocyte membrane stability, as well as phagocytosis and migration by neutrophils and macrophages. Component of the WAVE2 complex which signals downstream of RAC to stimulate F-actin polymerization. Required for stabilization and/or translation of the WAVE2 complex proteins in hematopoietic cells (By similarity). Within the WAVE2 complex, enables the cortical actin network to restrain excessive degranulation and granule release by T-cells. Required for efficient T-lymphocyte and neutrophil migration. Exhibits complex cycles of activation and inhibition to generate waves of propagating the assembly with actin. Also involved in mechanisms WAVE-independent to regulate myosin and actin polymerization during neutrophil chemotaxis. In T-cells, required for proper mechanistic target of rapamycin complex 2 (mTORC2)-dependent AKT phosphorylation, cell proliferation and cytokine secretion, including that of IL2 and TNF.
Synonyms: HEM1; IMD72
Tractability: Antibody: UniProt places it where antibodies can reach, with high confidence; its Gene Ontology location is reachable by antibodies, with high confidence; UniProt predicts a signal peptide or a membrane-spanning region; the Human Protein Atlas places it where antibodies can reach. PROTAC: ubiquitination databases record sites on it; its protein half-life has been measured.
Gene: Protein-coding gene on chromosome 12 (54,497,721 to 54,548,243, forward strand). Ensembl gene ENSG00000123338.
Subcellular location: Cell membrane; Cytoplasm
Subcellular location (Human Protein Atlas): Cytosol; Plasma membrane
Pathways (Reactome):
Signal Transduction: RAC1 GTPase cycle; RAC2 GTPase cycle; RAC3 GTPase cycle; RHO GTPases Activate WASPs and WAVEs; VEGFA-VEGFR2 Pathway
Immune System: Neutrophil degranulation; Regulation of actin dynamics for phagocytic cup formation
Disease: FCGR3A-mediated phagocytosis
Gene Ontology:
Molecular function: GTPase activator activity; protein binding; protein kinase activator activity; protein-containing complex binding; TORC2 complex binding
Biological process: actin polymerization-dependent cell motility; B cell receptor signaling pathway; chemotaxis; cortical actin cytoskeleton organization; erythrocyte development; intracellular signal transduction; maintenance of cell polarity; negative regulation of apoptotic process; negative regulation of cytotoxic T cell degranulation; positive regulation of actin filament polymerization; positive regulation of B cell proliferation; positive regulation of leukocyte migration; positive regulation of neutrophil migration; positive regulation of T cell proliferation; positive regulation of TORC2 signaling; response to xenobiotic stimulus; B cell homeostasis; cell migration; erythrocyte homeostasis; myeloid cell homeostasis; negative regulation of interleukin-17 production; negative regulation of interleukin-6 production; neuron projection morphogenesis; positive regulation of B cell differentiation; positive regulation of CD4-positive, alpha-beta T cell differentiation; and 9 more
Cellular component: cytoplasm; cytosol; extracellular exosome; membrane; plasma membrane; SCAR complex; ficolin-1-rich granule membrane; secretory granule membrane
Genetic constraint (gnomAD): Loss-of-function variants: 42 observed, 117.98 expected, observed/expected ratio (o/e) 0.36, 90% interval 0.28 to 0.46. The upper end of that interval is the gene's LOEUF score, 0.46, which puts it in group 2 of 6, group 1 being the genes least tolerant of losing a copy. Missense variants: 1,000 observed, 1,279.2 expected, observed/expected ratio (o/e) 0.78, 90% interval 0.74 to 0.82. Synonymous variants: 422 observed, 472.42 expected, observed/expected ratio (o/e) 0.89, 90% interval 0.82 to 0.97.
Gene-disease validity (ClinGen):
ClinGen rates the evidence that NCKAP1L causes each of these diseases.
immunodeficiency 72 with autoinflammation (autosomal recessive): Moderate.
Homologues: Orthologues: chimpanzee NCKAP1L (99% identical), macaque NCKAP1L (99% identical), pig NCKAP1L (96% identical), dog NCKAP1L (96% identical), rabbit NCKAP1L (95% identical), mouse Nckap1l (95% identical), rat Nckap1l (95% identical), guinea pig NCKAP1L (90% identical), tropical clawed frog nckap1l (72% identical), zebrafish nckap1l (60% identical), Drosophila melanogaster Hem (48% identical), Caenorhabditis elegans gex-3 (36% identical). Paralogues in human: NCKAP1 (59% identical).
Diseases named in the same sentence as NCKAP1L in open-access papers:
NCKAP1L is named in the same sentence as 62 diseases in open-access papers, as found by Europe PMC text mining. Sharing a sentence is not in itself a finding about the gene and the disease. The quoted sentences say what the papers report.
Immunodeficiency (11 papers, 2020 to 2025). Failure of the immune system to protect the body adequately from infection, due to the absence or insufficiency of some component process or substance. "A previous study has shown that mutations in NCKAP1L that abolished protein expression caused immunodeficiency, lymphoproliferation, and hyperinflammation in two human cases." (PMID 38190401, 2024). "For example, NCKAP1L deficiency has been shown to result in immunodeficiency, lymphoproliferation and excessive inflammation, with zebrafish nckap1l KD shown to cause defective neutrophil migration." (PMID 37047441, 2023). "In two unrelated patients of Middle Eastern origin, recessive mutations in NCKAP1L abolishing protein expression led to immunodeficiency, lymphoproliferation, and hyperinflammation with features of hemophagocytic lymphohistiocytosis." (PMID 32766723, 2020). "Biallelic mutations in NCKAP1L, a regulator of the actin cytoskeleton, cause immunodeficiency, lymphoproliferation, and hyperinflammation with features of hemophagocytic lymphohistiocytosis." (PMID 32766723, 2020). "Human HEM1 deficiency as a consequence of homozygous loss-of-function mutations in NCKAP1L causes a syndrome of immunodeficiency characterized by variable immune dysregulation including autoimmunity, lymphoproliferation, features of hemophagocytic lymphohistiocytosis (HLH) and atopic disease." (PMID 36870198, 2023). "For example, mutations in NCKAP1L contribute to inactivation of the AKT signaling pathway, thereby resulting in T cell proliferation and immunodeficiency." (PMID 34898354, 2021). "In contrast, NCKAP1L loss blunts AKT phosphorylation and modulates immunodeficiency." (PMID 34898354, 2021).
Autoimmunity (6 papers, 2022 to 2025). The occurrence of an immune reaction against the organism's own cells or tissues. "More recently, loss-of-function mutations in the human NCKAP1L gene (encoding Hem1) were associated with severe autoimmunity due to aberrant T and B cell function resembling the defects observed in Hem1-deficient mouse models." (PMID 38582757, 2024). "Among newly identified genes linked to IEIs include 3 independent reports of 9 individuals from 7 independent kindreds with severe primary immunodeficiency disease (PID) and autoimmunity due to loss-of-function mutations in the NCKAP1L gene encoding Hematopoietic protein 1 (HEM1)." (PMID 39026677, 2024). "Children with PID due to loss-of-function mutations in the NCKAP1L gene encoding for Hem-1 suffer from a variety of clinical manifestations, including recurring bacterial and viral infections, pneumonia, poor specific Ab responses, and autoimmunity resulting in high mortality." (PMID 35531955, 2022). "Mutations in the NCKAP1L gene encoding HEM1 have recently been found to result in severe primary immunodeficiency disease (PID), characterized by recurrent respiratory infections, hyperinflammation, autoimmunity, and high mortality." (PMID 40627451, 2025).
actinopathies (3 papers, 2021 to 2022). "Many actin-regulatory proteins are targets of BCR signaling and mutations in actin regulators such as Wiskott-Aldrich Syndrome protein (WASp), Arpc1B, Hem1/NCKAP1L, and Wdr1 result in autoimmune or immunodeficiency syndromes that have been termed actinopathies." (PMID 34336818, 2021).
atherosclerosis (3 papers, 2014 to 2025). A disease characterized by the build-up of fatty material and calcium deposition in the arterial wall resulting in partial or complete occlusion of the arterial lumen. "Within the shared CAD/atherosclerosis liver network between species, APBB1IP, PTPRC, NCKAP1L and INPP5D were captured as potential novel KDs which again have not been strongly investigated, validated or implicated in CAD previously." (PMID 38060277, 2023). "Similarly, when querying the liver KDs in the atherosclerosis HMDP liver tissue, we found Cidec is negatively correlated with aortic lesion area as well as numerous KDs including Inpp5d and Nckap1l positively correlated with aortic lesion area." (PMID 38060277, 2023).
breast carcinoma (3 papers, 2015 to 2024). "The messenger RNAs of NCKAP1L play a prognostic role in the tumor microenvironment of luminal breast cancer; higher NCKAP1L is associated with better prognostic ability." (PMID 39468330, 2024). "NCKAP1L was located at least 1Mb away from the GWAS-identified breast cancer risk variants." (PMID 39468330, 2024). "Besides, only NCKAP1L was reported in an unpublished TWAS as being associated with breast cancer risk." (PMID 39468330, 2024). "Analyses stratified by breast cancer subtypes found that SMARCC1, LSP1, and NCKAP1L are associated with luminal A and LSP1 with luminal B and ER-positive subtype." (PMID 39468330, 2024). "Stratification analyses by breast cancer subtypes identified three proteins, SMARCC1, LSP1, and NCKAP1L, associated with luminal A, luminal B, and ER-positive breast cancer." (PMID 39468330, 2024). "Analysis of rare missense variants identified evidence of associations of TMEM161A, SIPA1L1, and ERCC2 with overall breast cancer, RNF175 and NCKAP1L with ER-positive disease, and SLC22A10, PHAX, SMARCA2, EML5, NTRK3, and MED23 with ER-negative disease." (PMID 35884425, 2022). "When missense variants were assessed, three further associations were observed for overall breast cancer (TMEM161A, SIPA1L1, ERCC2), and a further seven were observed for subtypes (RNF175, NCKAP1L, PHAX, SMARCA2, EML5, NTRK3, MED23)." (PMID 35884425, 2022). "The best putative candidates in this group were TMEM161A, ERCC2, and SIPA1L1 for overall breast cancer, RNF175 and NCKAP1L for ER-positive disease, and PHAX, SMARCA2, NTRK3, EML5, and MED23 for ER-negative disease." (PMID 35884425, 2022).
primary immunodeficiency disease (3 papers, 2022 to 2025). "Loss-of-function variants in the NCKAP1L gene encoding Hem-1 were recently discovered to result in primary immunodeficiency disease (PID) in children, characterized by poor specific Ab responses, increased autoantibodies, and high mortality." (PMID 35531955, 2022). "Among the novel IEIs recently described include 3 reports describing 9 individuals from 7 independent kindreds with severe primary immunodeficiency disease (PID) due to loss-of-function (LOF) mutations in the NCKAP1L gene encoding the actin regulatory protein hematopoietic protein-1 (Hem1)." (PMID 40627451, 2025).
viral infections (3 papers, 2022 to 2024). "Recent reports of pathogenic variants in NCKAP1L, a hematopoietically restricted gene encoding the HEM1 protein component of the WRC, defined a novel disease involving recurrent bacterial and viral infections, autoimmunity, and excessive inflammation (OMIM 141180)." (PMID 35869404, 2022).
adenoma (1 paper, 2019). A neoplasm arising from the epithelium. "Genes NCKAP1L and DMD, identified in the main cluster of the cancer network, were identified as mutated in a considerable percentage of the cases of adenomas, adenocarcinomas and squamous cell neoplasms whose primary site was bronchus and lung, and which were registered at the GDC portal by TCGA." (PMID 31766738, 2019).
B-cell chronic lymphocytic leukemia (1 paper, 2024). "In another gene expression analysis, NCKAP1L was found to be significantly overexpressed in B-cell chronic lymphocytic leukemia (CLL) cells expressing high CD38, a cell marker associated with poor clinical outcome." (PMID 39026677, 2024).
colitis (1 paper, 2024). Inflammation of the colon. "Using Hem1pt/pt mice lacking Nckap1l expression to test IBD association, the authors found that Hem1 deficiency did not cause spontaneous colitis, but increased susceptibility to intestinal inflammation in the dextran sulfate sodium (DSS) mouse model of colitis." (PMID 39026677, 2024).
hepatocellular carcinoma (1 paper, 2019). A malignant tumor that arises from hepatocytes. "Regarding the information retrieved from the GDC portal on the potential biomarkers, the role of gene NCKAP1L in proliferation and invasion has previously been described breast and hepatocellular carcinoma." (PMID 31766738, 2019).
Intellectual disability (1 paper, 2021). "Although the de novo stop-gain variant of MED13L p.Arg1760∗ was previously reported in an intellectual disability case, we also identified de novo variants of PPP5C and NCKAP1L in the same individual with the MED13L variant." (PMID 33748132, 2021).
periodontitis (1 paper, 2025). An acute or chronic inflammatory process that affects the tissues that surround and support the teeth. "We identified HCK, NCKAP1L, and WAS as key diagnostic biomarkers for periodontitis-related unstable plaques and developed a diagnostic nomogram to facilitate clinical risk assessment." (PMID 40136451, 2025). "Following the criteria of an AUC > 0.7 and significant expression differences in datasets GSE613451 and GSE41571, we ultimately identified HCK, NCKAP1L, and WAS as biomarkers for unstable atherosclerotic plaques associated with periodontitis." (PMID 40136451, 2025). "By screening the node genes of the PPI network and applying various machine learning methods, we identified HCK, NCKAP1L, and WAS as biomarkers of periodontitis-related unstable plaques." (PMID 40136451, 2025). "Further analysis correlating the expression of periodontitis-related biomarkers with immune cell composition reveals a significant relationship between HCK and dendritic cells (DCs), while NCKAP1L is significantly correlated with gamma delta T cells and neutrophils." (PMID 40136451, 2025).
renal fibrosis (1 paper, 2025). A final common manifestation of a wide variety of chronic kidney diseases characterized by glomerulosclerosis and tubulointerstitial fibrosis. "This increased expression of NCKAP1L was also positively associated with the levels of collagen fiber deposition, Scr, and BUN, indicating a link to renal fibrosis." (PMID 40091743, 2025). "Altogether, these findings suggest that Nckap1l is a key factor that affects renal fibrosis after IRI, and that the effect of HNF3α is likely mediated through Nckap1l." (PMID 40091743, 2025). "Because Nckap1l levels are elevated in CKD patients and in animal models of renal fibrosis, and HNF3α regulates the transcription of Nckap1l in renal tubular epithelial cells, we examined the possible mechanism by which Nckap1l contributes to renal fibrosis." (PMID 40091743, 2025). "Consequently, it appears that the critical regulatory effect of HNF3α on renal fibrosis after IRI is mediated by its promotion of Nckap1l expression, although the precise mechanism warrants further exploration." (PMID 40091743, 2025). "Thus, the targeting HNF3α and Nckap1l appears to have potential as novel therapeutic avenue for treatment of renal fibrosis." (PMID 40091743, 2025). "To summarize, our findings suggest that HNF3α could promote the progression of renal fibrosis by directly regulating the transcription of Nckap1l, thereby altering cell migration." (PMID 40091743, 2025). "Because Nckap1l promotes cell migration and this effect is linked to the increased polymerization and relocation of F‐actin, these findings point to the critical function of HNF3α in promoting the transcription of Nckap1l, and suggest that activation of this pathway promotes renal fibrosis." (PMID 40091743, 2025). "Because HNF3α directly stimulates Nckap1l expression in renal tubular epithelial cells, we measured the levels of Nckap1l in CKD patients and in mouse models of renal fibrosis." (PMID 40091743, 2025). "Thus, the upregulation of Nckap1l in human patients with CKD and in murine models of renal fibrosis points to the importance of this protein in the pathogenesis of CKD." (PMID 40091743, 2025). "Thus, HNF3α appears to play a pivotal regulatory role in renal fibrosis after IRI, potentially by controlling the transcription of Nckap1l, increasing cell migration, and promoting the aggregation of F‐actin." (PMID 40091743, 2025).
squamous cell neoplasm (1 paper, 2019). A neoplasm that is composed of squamous epithelial cells. "Amongst the 28 cancer-exclusive genes, the gene NCKAP1L (NCK associated protein 1 like) was found to be affected in the 8.19% of the mentioned cases (N = 415) of lung and bronchus squamous cell neoplasms." (PMID 31766738, 2019).
cancer (6 papers, 2019 to 2025). A tumor composed of atypical neoplastic, often pleomorphic cells that invade other tissues. "The five EMRGs in our model—LOXL2, RUNX2, NCKAP1L, WFS1, and SPTBN1—have been implicated in diverse cancer-related processes." (PMID 41164190, 2025). "We found that 30 of these genes which included Nckap1l, Ncf1, Pla2g15, Unc93b1, Lrrc33, Rgs10, Gmfg, Rbm25, C3ar1, Ccdc88b, Fam105a, Gng11, Phc1, Rasa4, Dag1, Tyrobp, Tmsb4x, Cfp, Prkd1, Gp49a, Trem2, C1qc, Lyz2, Igfbp7, Rab30, Cxcl16, Egfl7, Ube2r2, Pltp, and Cfb, showed a relation with cancer." (PMID 32812032, 2020). "However, the biological roles of JCHAIN and NCKAP1L in human cancer have rarely been investigated." (PMID 33329695, 2020). "In pan-cancer, the expression levels of PTPRC, TLRB, PLEK, NCKAP1L, PGS18 and CLEC12A were positively correlated with GPR141." (PMID 40959105, 2025). "The results showed that PTPRC, TLR8, PLEK, NCKAP1L, RGS18 and CLEC12A displayed strong correlation with GPR141 in most cancer types." (PMID 40959105, 2025). "We performed correlation analysis of these six genes (PTPRC, TLR8, PLEK, NCKAP1L, RGS18 and CLEC12A) with GPR141 in pan-cancer." (PMID 40959105, 2025). "Amongst potential biomarkers, genes NCKAP1L and DMD are highlighted due to their implications in a considerable portion of lung and bronchus primary carcinomas." (PMID 31766738, 2019).
tumor (4 papers, 2018 to 2025). "In addition, RT-qPCR analysis revealed that LOXL2 and SPTBN1 were predominantly expressed in normal cell lines, whereas higher levels of NCKAP1L, RUNX2, and WFS1 were detected in tumor cell lines." (PMID 41164190, 2025).
brain disorder (1 paper, 2025). A disease affecting the brain or part of the brain. "Whether WAVE2, NCKAP1L and CYFIP2 function in T cells; WAVE1 and WAVE2 function in macrophages; or WAVE complex-mediated actin polymerization in peripheral and central immune cells is involved in pathogenic or protective mechanisms for brain disorders remains to be explored." (PMID 39774290, 2025).
NCKAP1L also shares sentences with these, for which no sentence is quoted: infection (6 papers); anemia (5); lymphopenia (5); hemophagocytic lymphohistiocytosis (3); autoimmune disease (2); Failure to thrive (2); inflammatory bowel disease (2); pneumonia (2); respiratory infections (2); abdominal aortic aneurysm (1); adenocarcinoma (1); age-related macular degeneration (1); allergic disease (1); alveolar proteinosis (1); amyloidosis (1); aortic aneurysm (1); asthma (1); autism (1); autoimmune lymphoproliferative syndrome (1); bacterial infection (1); biliary atresia (1); bronchiectasis (1); cardiovascular diseases (1); fibrosis (1); gastroenteritis (1); hematopoietic cancers (1); Hepatosplenomegaly (1); intestinal disease (1); liver fibrosis (1); lymphoproliferative disorders (1).
A further 14 diseases each share a sentence with NCKAP1L in 1 paper.